EGFR (epidermal growth factor receptor)
Diseases named in the same sentence as EGFR in open-access papers (continued):
Sharing a sentence is not in itself a finding about the gene and the disease.
adenocarcinoma (continued). "In non-adenocarcinoma cases, one EGFR Ex.19 deletion, one KRAS G12C mutation, two KRAS other mutations, and one MET Ex.14 skipping were detected with the ODxTT; meanwhile, no driver alterations were detected with the AmoyDx-multi test." (PMID 38730622, 2024). "All the EGFR-mutated patients had a histopathological diagnosis of adenocarcinoma and revealed multiple infection of HPV types 16 and 51, and two of them were smokers." (PMID 39205175, 2024). "Patients who survived longer than 90 days tended to have a higher frequency of non-adenocarcinoma histology, EGFR gene mutations, and therapeutic induction with immune checkpoint inhibitors (ICI)." (PMID 39355485, 2024). "Adenocarcinoma was strongly associated with Exon 19 deletion mutation in EGFR-positive patients, consistent with an Indian study finding EGFR mutations in 32% of NSCLC cases, mostly Exon 19 deletions." (PMID 39429333, 2024). "Of those 249 IA patients, EGFR mutations were most common in papillary-predominant (83.87%) and lepidic-predominant adenocarcinoma (83.78%), followed by acinar-predominant (66.88%) and solid-predominant carcinoma (0.00%)." (PMID 39364008, 2024). "Epidermal growth factor receptor (EGFR) mutations are prevalent in >50% of non-small cell lung cancer (NSCLC) cases with adenocarcinoma in Asia." (PMID 39165617, 2024). "The most common driver gene mutation in NSCLC is the epidermal growth factor receptor (EGFR), which is found in 45% of Asian patients with adenocarcinoma histology and in 20% of Caucasian patients." (PMID 39555453, 2024). "In particular, the mutational landscape driving adenocarcinoma incidence in East Asia has been linked to EGFR mutations and patient demographics, including age and sex." (PMID 38539567, 2024). "The postoperative pathological diagnosis was adenocarcinoma with an epidermal growth factor receptor mutation of exon 19 deletion." (PMID 38453764, 2024). "This article accurately diagnoses and retrospectively analyzes the clinical data of a case of ALK mutant adenocarcinoma in a male patient who developed an EGFR mutation with multiple metastases four years after surgery, and reviews the relevant literature." (PMID 39147711, 2024). "Of the patients, 19.2% had EGFR mutations, which is in line with the available literature, especially in the Asian population with a higher incidence of adenocarcinoma." (PMID 39850198, 2024). "Higher rates of positive epidermal growth factor receptor mutation and adenocarcinoma, especially invasive adenocarcinoma, have been reported in patients with cancer in the upper lung regions compared to other locations." (PMID 38730661, 2024). "We found noevidence of differences in sex (P = .018), age(P = .817), smoking status (P = .209),lymph node involvement (P = .357), early-stage adenocarcinoma(P = .153), lepidic growth adenocarcinoma(P = .018), or EGFR mutation(P = .652) between the two groups." (PMID 38206165, 2024). "Guidelines from prominent medical organizations recommend analyzing adenocarcinoma tumors or metastases for EGFR and ALK mutations, particularly in patients with a history of light or never smoking." (PMID 39429333, 2024). "Germline mutations of the EGFR gene were also described, which, if present, increase the incidence of adenocarcinoma, mostly in the presence of additional somatic mutations." (PMID 38953007, 2024). "Supraclavicular lymph node biopsy confirmed adenocarcinoma of pulmonary origin with positive epidermal growth factor receptor (EGFR) mutation." (PMID 39811212, 2024). "ASC harboring EGFR mutations can be treated with EGFR-TKI in a similar manner to Adenocarcinoma (ADC) harboring EGFR mutations." (PMID 39026979, 2024).
adenocarcinoma (continued). "In NSCLC, in particular in adenocarcinoma, mutations are common in epidermal growth factor receptor (EGFR) and Kirsten rat sarcoma viral oncogene homolog (KRAS)." (PMID 38926762, 2024). "This change in regulation is likely important for pathogenic EGFR signaling, because mutating a single C-terminal EGFR S-acylation site reduces tumorigenesis in an adenocarcinoma model." (PMID 39168183, 2024). "Six of the tested patients were positive for EGFR mutations; all of them had adenocarcinoma and underwent surgery+perioperative therapy." (PMID 38812106, 2024). "The PIONEER study reported a range of 22-62% EGFR mutations in adenocarcinoma patients across seven Asian regions." (PMID 39429333, 2024). "LCINS is often an adenocarcinoma carrying epidermal growth factor receptor (EGFR) gene mutations and is characterized by a higher prevalence in Asians, females, and is associated with radon exposure, occupational carcinogen exposure, and air pollution." (PMID 39315583, 2024). "It was found that pathological type (adenocarcinoma) was a risk factor for EGFR mutation in peripheral blood ctDNA (p<0.05), and smoking history was a protective factor for EGFR mutation in peripheral blood ctDNA (p<0.05) (Table-IV)." (PMID 39634906, 2024). "Genetic variations that are frequently detected in adenocarcinoma include EGFR, ALK, and ROS1 mutations." (PMID 39685930, 2024). "From 80 subjects included, only one patient was diagnosed with SCC and had EGFR variant, while the rest was diagnosed with adenocarcinoma." (PMID 38245692, 2024). "In contrast to better-known driver alterations in adenocarcinoma, such as EGFR, KRAS, and ALK, passenger mutations seem to contribute to the high somatic mutation rate in LUSC." (PMID 36873930, 2023). "In this retrospective observational study, we enrolled patients with resected stage III adenocarcinoma with EGFR mutations between January 2011 and December 2021." (PMID 37697233, 2023). "For example, for NSCLC adenocarcinoma with gain of function mutations in Epidermal Growth Factor Receptor (EGFR) as well as with EGFR gene amplification, tyrosine kinase inhibitors (EGFR-TKIs) have been developed." (PMID 37019897, 2023). "Soon after, she was diagnosed with a T3N2M0, Stage IIIB NSCLC adenocarcinoma, positive for the EGFR L858R mutation." (PMID 36923435, 2023). "Asian patients with adenocarcinoma have a higher epidermal growth factor receptor (EGFR) mutation frequency of about 51.4% overall." (PMID 36380563, 2023). "There is a significant association between EGFR status and VEGFa expression in the analyzed adenocarcinoma samples." (PMID 36766867, 2023). "Similar to the classic EGFR variants, EGFR ex20 ins/dup was found more common in Asian women, non- or light smokers, and adenocarcinomas." (PMID 37284196, 2023). "Tumors with EGFR mutations were more likely to be associated with an adenocarcinoma histology compared with EGFR wild-type tumors (79% versus 61%)." (PMID 37040387, 2023). "By incorporating adenocarcinoma subtype information, we achieved 100% sensitivity in predicting EGFR mutations in 37.3% of adenocarcinoma patients." (PMID 37407963, 2023). "Pathology for 24 patients (92.3%) revealed adenocarcinoma and 9 patients (34.6%) had additional mutations in actionable driver mutations (EGFR, ALK, BRAF, MET or ERBB2)." (PMID 37835426, 2023). "This is in alignment with the evidence of higher BrMs rates in adenocarcinoma subtype, especially in those harboring targetable mutations, such as EGFR and ALK rearrangements." (PMID 37035171, 2023). "Approximately 50% of Asian patients with adenocarcinoma harbor epidermal growth factor receptor (EGFR) mutations." (PMID 38094613, 2023). "Histologically, 16 cases were classified as adenocarcinoma of which two had sensitizing EGFR mutations with progression on EGFR inhibitors and platinum‐based chemotherapy." (PMID 36330681, 2023).
adenocarcinoma (continued). "Sixteen (70%) patients had adenocarcinoma, of which four patients harbored mutations in the epidermal growth factor receptor gene." (PMID 37653078, 2023). "MET gene amplifications can be observed in up to 4% of patients with adenocarcinomas and in up to 20% of those patients with EGFR mutations after immunosuppressive treatment." (PMID 36836402, 2023). "While transformation from adenocarcinoma (ADC) with EGFR exon 19 deletions and exon 21 L858R point mutations has been described, to our knowledge, no cases of transformation to SCLC from exon-18-mutated ADC have been reported." (PMID 36975478, 2023). "On this basis the present review describes the therapeutic strategies integrating medical and radiation oncology in patients with metastatic NSCLC (mNSCLC) adenocarcinoma with CNS involvement and EGFR activating mutations or ALK rearrangement." (PMID 36786970, 2023). "FAF1 expression was significantly higher in advanced pathological stage adenocarcinoma (p = 0.002), worse regional lymph node metastasis (p = 0.014), and positive EGFR mutation (p = 0.006)." (PMID 37999107, 2023). "More interestingly, we found that patients with pulmonary nodules carrying the DD genotype had an increased risk of adenocarcinoma and a lower probability of EGFR gene mutation (OR = 0.312, 95% CI, 0.101–0.968, p = 0.044)." (PMID 37371643, 2023). "Eight of the 28 non‐adenocarcinoma patients detected by SuperARMS had EGFR mutation, seven of which were positive both in tissue and plasma, one of which was only positive in tissue." (PMID 36621813, 2023). "A remarkable case of a female patient diagnosed ten years earlier reporting with stage IV adenocarcinoma of the lung with an EGFR mutation was also described." (PMID 36678867, 2023). "A total of 563 patients (42.0%) were tested for EGFR mutations (86% of tested patients had adenocarcinomas), with a larger proportion of stage IIIA patients being tested (49.3%) than both stage II (36.7%) and stage IB (38.9%)." (PMID 37958305, 2023). "The results revealed a higher prevalence of EGFR mutations in Asians, with approximately 45% of adenocarcinomas exhibiting this alteration, and Latin Americans, with over 33%." (PMID 37895255, 2023). "The most common histology was adenocarcinoma (78.2%), and driver‐gene mutations were observed in 9 patients (8 EGFR+, 1 ALK+)." (PMID 37076988, 2023). "Most of the patients who were tested for EGFR mutation (86.1%) had the most common histological NSCLC subtype of adenocarcinoma, reflecting that during the study period only patients with adenocarcinoma were routinely tested for EGFR mutation." (PMID 35719062, 2023). "Fifteen cases of small and EGFR mutation‐positive adenocarcinomas were collected, including AIS, MIA, and small invasive adenocarcinoma (SIA)." (PMID 37004157, 2023). "Of the 55 patients with recurrences, 38 (73.1%) developed adenocarcinoma, with 3 of them (5.7%) harboring EGFR mutations." (PMID 36902867, 2023). "The first successful targets of ‘driver mutations’ were epidermal growth factor receptor (EGFR)-activating mutations, most commonly deletions in exon 19 or point mutation L858R in exon 21, found in approximately 15% of adenocarcinomas." (PMID 37370772, 2023). "The most common histological subtype was adenocarcinoma [98 (86.0%)]; 33 (28.9%) patients harbored a sensitive EGFR mutation (del exon 19 or L858R) or an ALK rearrangement." (PMID 37916162, 2023). "Extensive studies of EGFR signaling in NSCLC have revealed that most mutations occur around the kinase domain in around 30% of adenocarcinoma cases and promote constitutive activation in a ligand-independent manner." (PMID 37111291, 2023). "In a recent study, a patch-level EGFR mutation prediction model was developed for adenocarcinoma (ADC) with a high patch-level area under the curve (AUC) on a test set containing frozen formalin-fixed paraffin-embedded tissues and biopsies." (PMID 37407963, 2023).
adenocarcinoma (continued). "(2020) reported that 10.8% of stage IV adenocarcinoma patients tested for EGFR mutations used EGFR-TKIs as a first-line strategy." (PMID 37920156, 2023). "Patient report: The L813R + R776C EGFR mutation was found in a 70-year-old male, current heavy smoker, of European descent, and with adenocarcinoma stage IIIA with acinar characteristics." (PMID 36629526, 2023). "Pathology for 25 patients (96.2%) in the wt-BRCA group revealed adenocarcinoma and 9 patients (34.6%) had additional mutations in actionable driver mutations (EGFR, ALK, BRAF, MET or ERBB2)." (PMID 37835426, 2023). "Previous surveys have established a connection between adenocarcinoma histology and the high prevalence of EGFR gene mutations." (PMID 37425232, 2023). "The most common NSCLC subtype is adenocarcinoma, in which epidermal growth factor receptor (EGFR) mutations are one of the most widely recognized genomic alterations." (PMID 37185611, 2023). "Still, it is also due to the introduction of new drugs starting from 2011 with tyrosine kinase inhibitors in EGFR-mutated adenocarcinoma and from 2017 with immune checkpoint inhibitors." (PMID 37370797, 2023). "There was a significant difference between GGO adenocarcinoma types and EGFR mutation rate (χ2 = 38.461, p < 0.001)." (PMID 37340599, 2023). "The evaluation of afatinib (Giotrif®) CSF levels was first described in a woman diagnosed with stage IV adenocarcinoma of the lung with an underlying mutation of the EGFR gene." (PMID 36678867, 2023). "The EGFR mutation is associated with a higher risk of metastatic recurrence in locally advanced stage III adenocarcinoma." (PMID 37697233, 2023). "Following the diagnosis of adenocarcinoma due to the EGFR mutation, the patient was prescribed the EGFR-TKI gefitinib at a dosage of 250 mg p.o. q.d." (PMID 37916176, 2023). "Previous studies have found that the incidence of EGFR-activating mutations in bone metastasis is higher than that in primary adenocarcinomas or metastases to other organs." (PMID 36232650, 2022). "This histological prevalence is similar to other studies, which have reported high EGFR mutation rates in patients with adenocarcinoma." (PMID 36613084, 2022). "Transformed SCLC mainly occurs in Asian patients with adenocarcinoma harboring EGFR-TKI-sensitive mutations (such as the EGFR ex19del/T790M mutation) who are nonsmokers." (PMID 35840984, 2022). "In order to illustrate the impact of pathological subtype on the prediction for EGFR mutation by the AI model, the same stacked ensemble model was re-tested in adenocarcinoma-only group in the training and testing cohort, respectively." (PMID 35624472, 2022). "Our study demonstrated that EGFR mutation-positive cases with high-grade patterns have a relatively higher risk of recurrence among stage IA–IB adenocarcinomas." (PMID 35266536, 2022). "This assumption is supported by previous findings, where EGFR-mutated adenocarcinomas had a higher frequency of ground-glass opacity and air-bronchogram than wild-type tumors." (PMID 36115683, 2022). "There was a strong association of EGFR mutations with adenocarcinoma, and older age population (>60 years), which showed a significant p-value of 0.005." (PMID 36613084, 2022). "Adenocarcinomas with epidermal growth factor receptor (EGFR) mutations and EML4ALK1 rearrangement are more frequently found to have brain metastases." (PMID 36620544, 2022). "Models for predicting EGFR mutations on imaging have been developed using a radiomics approach, but these methods only reflect generalized adenocarcinomas and lack specificity for pGGN." (PMID 36119545, 2022). "Successful responses to osimertinib rechallenge following intervening chemotherapy in EGFR T790M mutated adenocarcinomas have only sporadically been observed." (PMID 35884398, 2022).
adenocarcinoma (continued). "Epidermal growth factor receptor (EGFR) mutations are found in adenocarcinomas, and oral EGFR-tyrosine kinase inhibitors (EGFR-TKIs) show good responses." (PMID 35837103, 2022). "In contrast, adenocarcinomas with a predominant lepidic pattern were associated with significantly less frequency of EGFR mutations (p = 0.017)." (PMID 35740676, 2022). "The last four years of the period, EGFR mutation was registered for approximately 8 -10% of the adenocarcinoma patients, which is in line with the latest published quality reports by the CRN." (PMID 36523970, 2022). "In contrast, the proportion of branch mutation in Asian EGFR-mutant adenocarcinomas was 62.3%, which was similar to that of IMAs in our cohort." (PMID 34290355, 2022). "When limited to adenocarcinomas, the frequency of EGFR mutations detected was 31.8% (56/176) with ODxTT and 33.5% (59/176) with cobas EGFR (p = 0.7332)." (PMID 36203199, 2022). "All patients with adenocarcinoma (n=59) had molecular testing and 10 patients (5.1%) had EGFR activating mutations." (PMID 35795657, 2022). "In EGFR-mutated adenocarcinoma cells, lactate production, glucose-induced extracellular acidification rate, and glucose consumption were significantly decreased after treatment with TKIs, showing that EGFR signaling played a major role in aerobic glycolysis." (PMID 35515138, 2022). "The EGFR gene mutation rate in the tissue specimens and adenocarcinoma patients was comparatively higher, corresponding to the relevant research reports in other parts of Asia." (PMID 35606799, 2022). "Noronha, V., (2013) reported an EGFR mutation rate of 35% among NSCLC in the Indian population A large-scale Asian study on adenocarcinoma patients found the overall EGFR mutation rate to be 51.4%, while it was reported to be 30% in the East Asia population." (PMID 36613084, 2022). "This study suggests that it is important to recognize that clinicopathological poor prognostic factors of RFS for stage IB-IIIA adenocarcinoma vary according to EGFR mutation status." (PMID 36085020, 2022). "The subgroup analyses indicated that adjuvant EGFR-TKIs were superior in regard to DFS in most subgroups, including varied smoking status, EGFR mutations type, gender, age, Eastern Cooperative Oncology Group performance status and adenocarcinoma." (PMID 35346117, 2022). "According to a meta-analysis conducted to characterize the patterns of mutation incidence in NSCLC, the frequency of EGFR mutations was 47.9% in adenocarcinoma (ADC) and 4.6% in squamous cell carcinoma (SCC) in Asian populations." (PMID 35626123, 2022). "We further explored in-depth the relevance between EGFR mutation-related features and risk stratification of progression-free survival (PFS) in EGFR mutant advanced adenocarcinoma." (PMID 36052262, 2022). "And it is more likely for patients with adenocarcinoma to have an EGFR mutation than those with other NSCLC subtypes." (PMID 34766737, 2022). "It has been reported that EGFR mutation status is related to PD‐L1 expression, with lower PD‐L1 expression level noted in adenocarcinoma patients with EGFR mutation." (PMID 34841687, 2022). "We performed a total of 73 tests for the detection of T790M mutation in 73 plasma samples, from 41 patients with adenocarcinoma treated with first- or second-generation of EGFR TKIs." (PMID 35522668, 2022). "PPCs harboring epidermal growth factor receptor (EGFR) mutations are extremely rare, and the efficacy of EGFR-tyrosine kinase inhibitors in PPC is limited compared to their efficacy in EGFR-mutated adenocarcinoma." (PMID 35743969, 2022). "It is worth noting that the highest levels were observed in patients with adenocarcinoma and patients with EGFR mutations." (PMID 35409936, 2022). "EGFR exon 19 deletion and L858R mutation were more commonly observed in female patients and adenocarcinoma." (PMID 35061839, 2022). "All the patients had adenocarcinomas and activated EGFR mutations, including exon 19 deletion and L858R." (PMID 35562327, 2022).